BHLHE23 (basic helix-loop-helix family member e23)
Description:
May function as transcriptional repressor. May modulate the expression of genes required for the differentiation and/or maintenance of pancreatic and neuronal cell types. May be important for rod bipolar cell maturation (By similarity).
Synonyms: bHLHb4; bA305P22.3; Beta4; Beta3b
Tractability: No criterion of Open Targets' tractability assessment is met for any kind of drug.
Gene: Protein-coding gene on chromosome 20 (63,005,927 to 63,007,035, reverse strand). Ensembl gene ENSG00000125533.
Subcellular location: Nucleus
Gene Ontology:
Molecular function: protein binding; sequence-specific double-stranded DNA binding; DNA-binding transcription factor activity, RNA polymerase II-specific; E-box binding; protein dimerization activity
Biological process: axon development; positive regulation of transcription by RNA polymerase II; sensory organ development
Cellular component: chromatin; nucleus
Genetic constraint (gnomAD): Loss-of-function variants: 0 observed, 0.0767 expected, observed/expected ratio (o/e) 0, 90% interval 0 to 1.89. That is too few expected variants to judge how well the gene tolerates losing a copy. Missense variants: 401 observed, 273.92 expected, observed/expected ratio (o/e) 1.46, 90% interval 1.35 to 1.59. Synonymous variants: 204 observed, 132.26 expected, observed/expected ratio (o/e) 1.54, 90% interval 1.38 to 1.73.
Homologues: Orthologues: chimpanzee BHLHE23 (99% identical), macaque BHLHE23 (96% identical), pig BHLHE23 (91% identical), rat Bhlhe23 (80% identical), dog BHLHE23 (79% identical), mouse Bhlhe23 (79% identical), zebrafish bhlhe23 (52% identical), tropical clawed frog bhlhe23 (50% identical), Caenorhabditis elegans ngn-1 (16% identical), Drosophila melanogaster tap (16% identical), Drosophila melanogaster ato (15% identical), Drosophila melanogaster amos (14% identical), and 1 more. Paralogues in human: BHLHE22 (51% identical), OLIG2 (32% identical), OLIG3 (29% identical), OLIG1 (27% identical), NEUROD2 (22% identical), NEUROD6 (22% identical), NEUROD4 (22% identical), NEUROD1 (21% identical), ATOH1 (19% identical), NEUROG1 (19% identical), NEUROG2 (19% identical), NEUROG3 (18% identical), and 3 more.
Diseases named in the same sentence as BHLHE23 in open-access papers:
BHLHE23 is named in the same sentence as 5 diseases in open-access papers, as found by Europe PMC text mining. Sharing a sentence is not in itself a finding about the gene and the disease. The quoted sentences say what the papers report.
atherosclerosis (1 paper, 2022). A disease characterized by the build-up of fatty material and calcium deposition in the arterial wall resulting in partial or complete occlusion of the arterial lumen. "Interestingly, expression of the BHLHE23 gene can be suppressed by environmental chemicals, including those found in the tobacco smoke, polycyclic aromatic hydrocarbons, biphenol A, acrylamide, dietary fats, and many of them are well known risk factors for atherosclerosis." (PMID 35203469, 2022).
endometrial cancer (1 paper, 2021). Primary or metastatic malignant neoplasm involving the endometrium (mucous membrane that lines the endometrial cavity). "In humans, Bhlhe22 has been identified as a highly methylated gene in endometrial cancer with potential epigenetic biomarkers in cervical scrapings, while Bhlhe23 has been linked to mammalian retinal development." (PMID 34306008, 2021).
BHLHE23 also shares sentences with these, for which no sentence is quoted: cancer (1 paper); cognitive decline (1); night blindness (1).